STAT3 (signal transducer and activator of transcription 3)
Diseases named in the same sentence as STAT3 in open-access papers (continued):
Sharing a sentence is not in itself a finding about the gene and the disease.
tumor (continued). "When the M2c macrophage is in a microenvironment of tissue remodeling, when the values of STAT3 are between 0.35 and 0.65 and STAT6 are between 0.1 and 0.7 the macrophage will transit to a M2d phenotype with the capacity to regulate the growth of tumor cells." (PMID 37283734, 2023). "In contrast, STAT3-depletion in FAK-wt cells had no impact on tumour growth despite driving a notable influx of CD8 T-cells into the tumour mass." (PMID 36977556, 2023). "With tumor growth, CD146 was downregulated via TME-induced STAT3 activation." (PMID 37308559, 2023). "It was reported that the BDNF/TrkB axis can promote several important biological processes in several types of cancer, such as cell proliferation, tumor immunosuppression, drug resistance, resistance to anoikis, activation of PI3K/AKT and JAK/STAT3 pathways, EMT, and angiogenesis." (PMID 37679418, 2023). "In addition, various studies have shown that STAT3/MYC signaling can regulate tumor energy metabolism and the microenvironment to impact tumor cell proliferation and metastasis." (PMID 36873736, 2023). "However, TGF- β promotes the development of IL-17+IL-22 + T cells, and the produced IL-22 can regulate the tumor niche and promote the occurrence of CAC by activating transcription factor STAT3 to promote the gene expression of core stem cells." (PMID 38273841, 2023). "In this last situation, the macrophage will transit to a pro-tumor and regulatory hybrid regardless of the expression of STAT3." (PMID 37283734, 2023). "HMGA2 can effectively adjust EMT through the PI3K/AKT, MAPK/ERK, TGFB/Smad, NFrB, and STAT3 signaling pathways, enabling HCC cells to invade local tissues, get the penetrating ability of intravascular, and give birth to offspring with the tumor-initiating ability." (PMID 37689710, 2023). "In contrast, expression of C3, SFRP2, STAT3, IL-6 and THY1 was increased in tumor-distal stroma." (PMID 37350578, 2023). "However, there is a major gap in our understanding of the mechanism by which STAT3 regulates these proinflammatory and anti-inflammatory genes to suppress GBM tumor immune responses." (PMID 37242454, 2023). "Kruskal–Wallis non‐parametric tests showed patients with high stromal expression of STAT3 had reduced CD4+ T‐cell counts within the tumour (p = 0.001) but not the stroma (p = 0.279) in triple negative cases." (PMID 37199043, 2023). "We found that within the tumor epithelium, it was Stat3 and not Stat5 signaling that was most abundant, with little to no detection of Stat5a." (PMID 37164949, 2023). "Other studies showed that unlike its activation status in primary tumor tissues, STAT3 is continuously activated in brain metastasis." (PMID 37894348, 2023). "The activated STAT3 pathway, in response to the binding of IL-6 secreted to its glycoprotein 130 (GP130) receptor, promotes tumour progression through the induction of various target genes involved in tumour cell survival, proliferation, angiogenesis, metastasis, and cell adhesion." (PMID 36979673, 2023). "Therefore, we examined the levels of STAT3 and p-STAT3 protein and determined that WCP significantly reduced the expression of p-STAT3 in tumor tissue." (PMID 37110586, 2023). "Moreover, p-STAT3 levels were significantly decreased with combined treatment of dasatinib plus erlotinib, and dasatinib plus erlotinib with gemcitabine in the PKT tumor samples." (PMID 36902166, 2023). "We found that tumor cells in 36.4% (4/11) cases of HES1 (−) group were positive for phospho-STAT3 while only 9.1% (1/11) of HES1 (+) cases were positive for phospho-STAT3 but statistical significance was not reached." (PMID 37749297, 2023).
tumor (continued). "STATs including STAT1–6 may exacerbate cell growth and cancer development (STAT3 and STAT5) and regulate the anti-tumor immune responses for tumor control (STAT1 and STAT2)." (PMID 38094755, 2023). "Strikingly, ablation of METTL3 in myeloid cells promoted tumor growth and metastasis, associated with decreased YTHDF1-mediated translation of SPRED2 and increased activation of NF-kB and STAT3 through the ERK pathway, leading to increased tumor growth and metastasis." (PMID 37369946, 2023). "Indeed, a low STAT1/high STAT3 ratio highlighted a faster tumor growth in xenografts compared to high STAT1 and low STAT3 expressions, which were characterized in contrast slower ones." (PMID 36982677, 2023). "In addition, IL-6 was detected in MDCS, and the IL-6R-neutralizing antibody inhibited both STAT3 activation and tumor proliferation induced by MDCS stimulation in both tumor cell lines." (PMID 36961655, 2023). "Accumulating reports have illustrated that miR-182, as a dual-role regulator, directly or indirectly regulates the expression of a wide range of genes and modulates the activity of various signaling pathways involved in tumor progression, such as JAK / STAT3, Wnt / β-catenin, TGF-β, and P13K / AKT." (PMID 37438760, 2023). "Furthermore, after intervening of STAT3, the effect of ARF6 on tumor-promoting was weakened, which demonstrated ARF6 functioned through STAT3 signaling in HCC." (PMID 37716993, 2023). "While we did not profile the antigen repertoire of cells following co-depletion of FAK and STAT3, we found that STAT3-depletion resulted in substantial infiltration of CD8 T-cells into tumours independent of FAK expression status." (PMID 36977556, 2023). "Both tumour cell lines were cultured with 15 μM K1836 for 72 h (with repeated supplementation every 24 h, as it was previously observed that STAT3 inhibition was not permanent and lasted for ~24 h; data not shown)." (PMID 36825563, 2023). "Moreover, TAMs can be redirected to M1 phenotype that promotes tumor immune response through NF-κB, STAT1, and STAT3 pathways." (PMID 37241759, 2023). "To address whether CMTR1 regulates tumor cell proliferation and immune response through STAT3, we overexpressed CMTR1 in STAT3-knockdown RKO cells." (PMID 37024465, 2023). "In the past, many reports have shown that VCAM1 and STAT3 are closely related, but the specific mutual regulation mechanism is not clear at present,especially in tumor microenvironment." (PMID 37563649, 2023). "Furthermore, in vitro analysis on TNBC cell lines (MDA-MB-231 and MDA-MB-468) also showed that through the activation of STAT3/MAPKs/AKT pathway, IL-22 enhances tumor cell migration and their resistance to paclitaxel chemotherapy in a dose-dependent manner." (PMID 37835465, 2023). "Tumor growth was reduced as well as β-catenin, transcription factor 4 (TCF4), protein kinase B (AKT), signal transducers and activators of transcription 3 (STAT3), and proliferating-cell nuclear antigen (PCNA) expression." (PMID 36986798, 2023). "Thus, higher the expression of STAT1, STAT2, STAT3, STAT4, STAT5A, and STAT5B, the lower the tumor purity." (PMID 36968603, 2023). "Likewise, exosomes derived from bladder cancer cells such as MB-49 induce macrophage M2 polarization via activating AKT/STAT3/6 and inhibiting the PTEN signaling pathway leading to an immunosuppressive tumor microenvironment that facilitates tumor progression." (PMID 38188673, 2023). "The tumor suppressive activities of SHP1 and SHP2 occur mainly through their inactivation of STAT3." (PMID 37298405, 2023).
tumor (continued). "In addition, NLK regulates phosphorylation and O-GlcNAcylation of STAT3 by binding to STAT3, thereby inhibiting CCL2 expression, in which it inhibits macrophage recruitment in the tumor microenvironment (TME)." (PMID 38008713, 2023). "Upregulation of IL-6 in plasma levels of mice has been shown to promote tumor growth, angiogenesis, metastasis, and the expansion of cancer stem cells, as well contribute to multidrug resistance via gp130/MAPK/STAT3-mediated activation of C/EBPβ/δ transcription factors." (PMID 38067195, 2023). "Importantly, we showed that combined treatment with selumetinib and pacritinib, a JAK/STAT3 pathway inhibitor, effectively decreases SHH MB tumor progression." (PMID 37726268, 2023). "Since we identified STAT3 as a downstream transcription factor modulated by ROR1 expression, we also investigated whether ROR1+ tumor cells are pSTAT3+ (Y705)." (PMID 37400436, 2023). "Moreover, FABP5 promotes tumor angiogenesis and activates the IL6/STAT3/VEGFA pathway in HCC, as evidenced by studies." (PMID 37576389, 2023). "Another study showed that ectopic IL-8 expression in tumor-adjacent adipocytes converted adipocytes into CAAs, with high levels of NF-κB and NF-κB targets (leptin/IL-8/IL-1 and an active pre-oncogenic STAT3-dependent EMT phenotype), on BCCs and in orthotopic tumor xenografts in mice." (PMID 36880535, 2023). "In addition, RUNX1 has been reported to mediate tumor function by transcriptionally regulating EGFR expression, activating downstream STAT3." (PMID 38057816, 2023). "Nonetheless, colivelin diminished the tumor-inhibiting impact of nuciferine, suggesting that nuciferine might partially impede the advancement of OSCC by suppressing the STAT3 signaling pathway." (PMID 37833979, 2023). "ATXN3-induced Pd-l1 transcription was promoted by tumor microenvironmental factors, including the inflammatory cytokine IFN-γ and hypoxia, through protection of their downstream transcription factors IRF1, STAT3, and HIF-2α." (PMID 38038129, 2023). "Other studies, especially those related to tumor diseases such as ovarian cancer and glioma, have shown that activation of the JAK/STAT3 signaling axis facilitates M2 macrophage polarization and affects disease progression by activating or inhibiting related cytokines." (PMID 37081874, 2023). "In fact, higher STAT3/pSTAT3 and IL-6R expression was found in CAFs compared to tumor cells (data not shown)." (PMID 36639824, 2023). "Moreover, in an in vitro experiment with dog BC cells, MDSCs-secreted IL-28 stimulated STAT3 in tumor cells, inducing EMT and promoting tumor cell migration." (PMID 37465670, 2023). "The role of CD24 is highlighted by the overexpression on different tumors, and knock-down of CD24 expression revealed its function in tumor cells: CD24 depletion reduced cell proliferation, enhanced sensitivity to undergo apoptosis, and modulated STAT3-mediated gene expression." (PMID 37626918, 2023). "Still, the role of STAT3 and STAT5 kinase proteins, as well as their interaction in various tumor processes, are to be detailed to develop therapeutic strategies selectively blocking or activating STAT3 and/or STAT5 in hematological malignancies and other cancers." (PMID 36765714, 2023). "JAK2/STAT3 belongs to non-receptor tyrosine kinases, playing a crucial role in the proliferation and apoptosis of tumor cells." (PMID 37895015, 2023). "Activated STAT3 was readily detected in non-epithelial cells of tumor sections, but not adjacent normal tissue." (PMID 38375204, 2023). "Furthermore, we evaluated the STAT3 pathway due to its importance in the regulation of IBC growth and tumor progression described by us and others." (PMID 36902125, 2023). "Moreover, STAT3 can continue to activate downstream PKC-δ and promote tumor survival in multiple ways." (PMID 37964870, 2023).
tumor (continued). "Moreover, mTORC1 can activate COX-2 transcription by phosphorylating STAT3 and enhancing the interaction with COX-2 promoter in the colonic epithelium, thus recruiting T helper-17 (Th17) cells and promoting tumor growth." (PMID 37875976, 2023). "STAT3 can also regulate H3K4me3 of its target genes in T cells under Th17 cell-polarizing conditions and recruit DNA methyltransferase 1 (DNMT1) to gene promoters to silence tumor suppressor genes, such as SHP-1, in malignant T lymphocytes." (PMID 36740715, 2023). "SLN STAT3 decoy also showed a higher rate of tumor apoptosis than STAT3 that was not delivered in a nanoparticle." (PMID 37173951, 2023). "Taken together, our study shows that the anti-tumor effect of morin/Dox co-treatment is due to the suppression of FOXM1 and attenuation of EGFR/STAT3 signaling pathways in MDA-MB-231 TNBC cells, which suggests that morin offers a means of improving therapeutic efficacy in TNBC patients." (PMID 37242455, 2023). "However, in our recent in vivo study, we demonstrated a gender-specific correlation between STAT3 expression and KRAS-mutant NSCLC; female mice with tumor-cell-specific STAT3 deletion showed decreased tumorigenesis while males had the opposite outcome." (PMID 36899885, 2023). "Based on our RNA-sequencing data, the Hallmark GSEA results indicated that BLACAT3 knockdown enriched EMT, IL6/JAK/STAT3, inflammatory response, KRAS, and TNFA/NF-κB pro-inflammatory signaling along with other gene sets related to tumor angiogenesis and metastasis." (PMID 37612524, 2023). "This was associated with a reduction in granzyme-B positive intratumoural staining when compared with FAK-/- and FAK-/- STAT3 shRNA tumours, implying a lack of effective CD8 T-cell engagement in the context of FAK-wt tumours." (PMID 36977556, 2023). "In addition to direct impacts on tumor cells, IL-6 and downstream JAK/STAT3 pathway also have profound effects on tumor immunosuppressive environment." (PMID 37069669, 2023). "And cisplatin and doxorubicin induced ATC cell death were synergistically promoted by silencing ATC stem cell markers; Intervention of JAK/STAT3 and NF-κB signals in ATC CSCs could effectively impede tumor growth in vivo." (PMID 37501099, 2023). "Moreover, STAT3 activation, triggered by IL-6 or TGF-β/LIF system, plays a role in EMT induction in different types of tumours." (PMID 37368660, 2023). "Notably, Cluster 1, 2, and 4 showed better response to ICIs, which should be due to TME supporting anti-tumor immunity, including IL6/JAK/STAT3 signaling, tumor necrosis factor (TNFA, TGFB) and interferon (IFNA, IFNG) pathways." (PMID 36817452, 2023). "Moreover, increased phosphorylation of STAT3 and expression of STAT3 target genes, NANOG and C-MYC in CD24+ OCSC, when inhibited with JAK2, induces cytotoxicity in CD24+ cells, reduces tumor metastasis, and prolongs overall survival." (PMID 37445860, 2023). "On one hand, elafin was related to an unfavorable prognosis of OC patients which involved apoptosis of tumor cells and the IL-6/JAK/STAT3 signaling pathway; on the other hand, a high expression of elafin participated in immunotherapy for tumors, indicating an ideal survival situation." (PMID 36742380, 2023). "Additionally, a positive feedback loop was described, including IL6/STAT3, IL1/NF-κB, and TNF/AP-1 signaling pathways, which maintain the state of inflammation in the tumor." (PMID 36825204, 2023). "In conclusion, we discovered a previously unknown pro‐tumorous mechanism in which the CYP2E1‐PPAR‐γ‐STAT‐1/NF‐κB/STAT‐3/STAT‐6 axis induced GBM cell proliferation and inhibited apoptosis to fuel tumorigenesis and tumor growth." (PMID 37283464, 2023). "CM also reduced the expression of JAK2 mRNA and STAT3 mRNA, although not significantly (P > 0.05), and reduced PD-L1 mRNA in tumor tissue compared to the control group (P < 0.05)." (PMID 38116545, 2023).
tumor (continued). "However, within the tumor microenvironment (TME), tumor cells and their targets such as STAT3, IRF8, C/EBPβ, and Notch can inhibit the differentiation of IMCs." (PMID 37857728, 2023). "The overall expression of STAT3 and JAK2 in the tumor tissues was hardly affected." (PMID 38202610, 2023). "As CIN fuels karyotypic heterogeneity during tumor cell evolution, CIN will likely promote selection of karyotypes that promote activity of pro-tumorigenic non-canonical NF-κB and STAT3 signaling and inhibit tumor-suppressive STAT1 signaling programs." (PMID 37561163, 2023). "Furthermore, there are reported data on STAT3 and STAT5 as tumor suppressors and their regulatory function in relation to the antitumor effect of immune cells." (PMID 36765714, 2023). "Furthermore, IL-6 favors tumorigenesis by creating an immunosuppressive tumor microenvironment, as the induction of JAK/STAT3 signaling has an inhibitory effect on, for example, dendritic cells, effector T cells, and natural killer cells." (PMID 38250802, 2023). "Additionally, Western blot analysis of tumor tissues demonstrated that theasinensin A plus nimotuzumab resulted in a greater suppression of p-EGFR, p-ERK1/2, p-STAT3 and p-GSK3β." (PMID 37762316, 2023). "Moreover, these tumor-derived cytokines and factors can activate and enhance STAT3 signaling in the TME and tumor cells, which promotes tumor progression and impairs antitumor immunity." (PMID 38001876, 2023). "The effect of TAM with active STAT3 leads to the secretion of interleukin (IL)-1β, which promote GBM growth by also allowing the activation of STAT3 and nuclear factor-kappa B (NF-kB) signaling in tumor cells." (PMID 37190507, 2023). "Given the shared features between tumor cells and pulmonary endothelial cells in PAH patients, and the beneficial effects of the inhibitor treatment of Hsp110-STAT3 interaction in these diseases, here we next tested the influence of Hsp110 on the regulation of the downstream STAT3 pathway in HPAECs." (PMID 37978368, 2023). "The average expression values of STAT1 (p < 0.001), STAT2 (p < 0.001), STAT3 (p < 0.001), STAT4 (p < 0.001), STAT5A (p < 0.001), STAT5B (p < 0.001), and STAT6 (p < 0.001) among immune subtypes C1-C6 in all tumor types were identified to have notable differences." (PMID 36968603, 2023). "Consequently, STAT3 has emerged as a prospective molecular target and biomarker for OSCC, with STAT3 inhibitors exhibiting effectiveness in restraining tumor growth and metastasis in OSCC." (PMID 37946196, 2023). "p-STAT3 alters autophagy and anoikis, two apoptotic processes that normally eliminates unwanted cells and the lack or reduction of their actions contribute to ADR and the progression of the tumor or hematological cancer." (PMID 36902166, 2023). "All these findings suggest that KDF1, which activates STAT3 and the downstream AKT pathway in LUAD, acts as a tumor-promoting factor and may represent a therapeutic target." (PMID 38137415, 2023). "We suggest that this double positive feedback loop of XIST and STAT3 may contribute to the dysregulation of XIST in BC and other tumor types." (PMID 36922677, 2023). "Furthermore, ZSW promotes STAT3 ubiquitination, inhibits the proliferation of TNBC cells in vitro, and attenuates tumor growth with manageable toxicities in vivo." (PMID 37173892, 2023). "IL-6/JAK2/STAT3 activation is mediated by the upregulation of EMT-induced transcription factors (e.g., Snail Zeb1, JUNB and Twist-1) to induce EMT, together with enhancing tumor cell migration and motility by activating the adherent patch kinase (FAK)." (PMID 36923251, 2023). "Moreover, previous studies have demonstrated that IFN‐γ, as an essential effector molecule for immune responses, can induce tumour progression and stimulate the expression of PD‐L1 via the JAK/STAT3 signalling pathway." (PMID 37480214, 2023). "Through enhancing STAT3-induced expression of IL-6, LEISA could promote tumor progression, which reveals the crucial role of LEISA in LAD." (PMID 36813772, 2023).